ENSG00000285978 (novel transcript)
Gene: Protein-coding gene on chromosome 5 (178,694,605 to 178,729,335, reverse strand). Ensembl gene ENSG00000285978.
Genetic constraint (gnomAD): Missense variants: 64 observed, 89.49 expected, observed/expected ratio (o/e) 0.72, 90% interval 0.58 to 0.88. Synonymous variants: 38 observed, 37.53 expected, observed/expected ratio (o/e) 1.01, 90% interval 0.78 to 1.33.